E2F3 (E2F transcription factor 3)
Diseases named in the same sentence as E2F3 in open-access papers (continued):
Sharing a sentence is not in itself a finding about the gene and the disease.
tumor (continued). "Either forced expression of miR-128-1 or Aza/PBA treatment inhibited migration and invasion of tumor cells in vitro, and E2F3 was found to be a direct target of and downregulated by miR128-1 in vitro and in vivo." (PMID 28947999, 2017). "Here's the section that summarizes the better-characterized contacts between tumor-related miRNAs and E2F3." (PMID 28947999, 2017). "Has-miR-377-3p also was demonstrated have tumor suppressive role and inhibited tumormetastasis by targeting E2F3 in NSCLC cell." (PMID 28887510, 2017). "Taken together, our data indicated that E2F3 triggered tumor cell growth and proliferation concomitantly with HIF-2α level." (PMID 28903320, 2017). "The reduction of miR-377–3p and let-7e leads to tumor progression through the miR-377–3p/E2F3 and let-7e/NRAS signaling pathway." (PMID 29026116, 2017). "For example, specific deletion of Pten in stromal fibroblasts or E2f3 in macrophages modifies tumour growth and metastasis, respectively." (PMID 28381598, 2017). "E2F3 expression was also significantly different in tumor size (P = 0.049), metastasis status (P = 0.016), lymph node status (P = 0.039), stage (P < 0.001), and T stage (P < 0.001)." (PMID 28740578, 2017). "It has been reported that miR-34a acted as a tumor suppressor in AML by inhibiting E2F3, resulting in blocking the transition from cell cycle G1 to S phase." (PMID 28947999, 2017). "E2F3 is not only required in normal proliferation, but also the key regulator on limiting the proliferation of tumor cell lines." (PMID 27351135, 2016). "In a xenograft model, PPIX treatment decreased overall growth and average tumor volume, which paralleled E2F3 inhibition." (PMID 25714015, 2015). "Our results highlight the significance of miR-145 as a tumor suppressor in cell proliferation by targeting E2F3 in GC." (PMID 25762621, 2015). "In summary, we have combined experimental and clinical studies to establish MicroRNA-424/Akt3/E2F3 axis functions as tumor suppressor in HCC growth." (PMID 26315541, 2015). "We discovered that PPIX treatment markedly increased miR-199a-5p levels in tumor cells, and this effect resulted in the inhibition of E2F3, a key regulator of G1/S transition and tumor growth." (PMID 25714015, 2015). "The most novel finding of the present work is that silencing of E2F3 severely restricts the fraction of Her2+ tumor cells undergoing mitosis that strongly correlates with suppressed tumor growth." (PMID 26512919, 2015). "A genetic cross of MMTV-Neu mice into an E2F1 null, E2F2 null, or E2F3 heterozygous background revealed significant changes in tumor progression specifically reductions in tumor latency and metastasis with E2F1 or E2F2 loss." (PMID 26682278, 2015). "In that work, a Kaplan-Meier survival plot revealed a significant acceleration in tumor onset when E2F1 was lost and a delay in tumor onset when E2F2 or E2F3 was lost." (PMID 26474282, 2015). "In the existing GEO database (GSE25097), E2F3 mRNA levels were also greater in HCC than in adjacent non-tumor liver tissues." (PMID 25714015, 2015). "Overall, these experiments demonstrated that silencing of E2F3 suppresses tumor growth and tumor mass of HCC1954 cells, while effects of GFP-Nek2 overexpression in HCC1954 cells silenced for E2F3 are inconclusive." (PMID 26512919, 2015). "To identify mechanisms responsible for the reduced tumor growth of cells silenced for E2F3, we first performed histopathology of tumor sections." (PMID 26512919, 2015). "E2F3 levels were greater in all of the classified mesenchymal tumor cell lines compared with the epithelial ones (The basal E2F3 levels were inconsistent in Hep3B)." (PMID 25714015, 2015). "In particular, E2F3a, a major form of E2F3 expressed in quiescent cells, plays a role in regulating G1/S transition, facilitating tumor growth and apoptosis." (PMID 25714015, 2015).
tumor (continued). "E2F3 protein levels were significantly upregulated in a large fraction of human tumor specimens (51 out of 59 sets of paired HCC and adjacent non-tumor samples)." (PMID 25714015, 2015). "More recently, several miRNAs, such as miR-34a, miR-20a and miR-125b have been reported to inhibit cell proliferation by negatively regulating E2F3 in tumor cells." (PMID 25367080, 2014). "Our results showing that miR-503 targets molecules both upstream (cyclin D3) and downstream (E2F3) of Rb, an archetypal tumor suppressor, provide new insight into tumorigenesis." (PMID 23967867, 2013). "Ectopic expression of miR-34a in head and neck cell lines significantly inhibited tumor cell proliferation, migration and colony formation by downregulating the expression of E2F3 and survivin." (PMID 22629428, 2012). "Hsa-miR-16, mentioned previously to be anti-correlated in tumours with several potential mRNA targets including E2F3, C8ORF30A, and SCAMP5, is significantly positively correlated with CDC25C." (PMID 22452920, 2012). "Promoters of upregulated genes in tumor were associated with binding sites of cell cycle regulators such as AP1-like factors, STAT, and E2f, of which Atf3, Jun, and E2f3 were significantly upregulated in both transgenic and tumor cells." (PMID 21464922, 2011). "To establish the expression levels of E2F3 protein, we performed a western blot analysis and we observed that E2F3 was markedly overexpressed in tumor samples." (PMID 20421977, 2010). "The highly statistically significant decrease in the levels of KIF14 mRNA expression (p<0.01) and E2F3 mRNA expression (p<0.001) in chemotherapy-treated cases shows the effect of chemotherapy on proliferative tumor cells." (PMID 19190782, 2009). "Enhancer of Zeste Homolg 2 (EZH2) expression is regulated by RUNX1, STAT3 and E2F3 and high expression of EZH2 gene is associated with the tumor death and also correlated to the pathological stage." (PMID 20025723, 2009). "This is the first report on the levels of two important candidate genes (KIF14 and E2F3) for proliferation of RB tumor simultaneously done in a larger cohort with phenotype association." (PMID 19190782, 2009). "Expression of E2F3 as well as DEK increased on average in tumor vs. normal tissues (3-fold and 2.5-fold, resp)." (PMID 15876350, 2005). "Importantly, rescue experiments confirmed that E2F3 overexpression reversed the anti-tumor effects of circ_0001741 knockdown, functionally validating this axis." (PMID 41372977, 2025). "Additionally, E2F3 was shown to activate cell cycle-related pathways, reinforcing its role in tumor proliferation." (PMID 41291892, 2025). "Some of these tumours were associated with amplification or overexpression of CCNE1, as we characterized it in MPM_31 and MPM_34 cell lines; and/or with high transcript levels of E2F1, or E2F3 in the peculiar M631PT patient in Bueno's cohort." (PMID 36453028, 2024). "Compared with Cluster1, Cluster2, with poorer prognosis, had chromosomal amplification of various tumor-promoting gene loci, such as E2F3, MYC, and GATA3, and partial or complete deletion of the chromosome where the tumor suppressor gene PTEN and RB1 loci are located." (PMID 37767092, 2023). "The expression of E2F3 in tumor tissues was detected through an IHC assay." (PMID 37456248, 2023). "We conducted qRT-PCR for testing lncRNA H19, miR-194, and E2F3 levels in the formed tumor tissues." (PMID 37253635, 2023). "Results suggested that the miR-363 might reduce tumorigenicity and tumor progression in a nude mouse model, which further confirmed that miR-363 might suppress cell proliferation, migration and invasion by targeting E2F3 in CRC." (PMID 37283793, 2023). "On the other hand, Circ-E2F3 was shown to be increased in RB tissues and cells, and silencing of circ-E2F3 suppressed RB cell proliferation, migration, invasion, and triggered apoptosis in vitro, as well as reduced RB tumor development in vivo." (PMID 35865469, 2022).
tumor (continued). "In the absence of RB1, E2F3 acts as a key driver for cell cycle progression and hence, its overexpression is associated with tumor progression and poor prognosis in Rb patients." (PMID 35359459, 2022). "Transcription factor E2F3 plays critical roles in cell proliferation, cell cycle distribution, and cell apoptosis in both tumor and primary cells by acting as a target for various miRNAs (including miR-432-5p) that are closely correlated with tumor stage and poor survival." (PMID 35091535, 2022). "Furthermore, the levels of E2F3 expression were also significantly higher in the clinical CCA tumor tissues than the paracancerous tissues." (PMID 35091535, 2022). "Generally, E2F1/E2F3, as an important node molecule of cell signaling network, participate in the transcriptional regulation of many important genes through dialogue with other signaling pathways, including NF-κB, and are tumor therapy targets." (PMID 36175803, 2022). "E2F3 is involved in various human tumors as a tumor promoter." (PMID 36619866, 2022). "Moreover, both TAM-secreted exosomes and hsa_Circ_0020256 induced increases in the numbers of Ki67 and E2F3 positive cells in xeno-engrafted CCA tumor tissues, while hsa_Circ_0020256 siRNA reversed those increases." (PMID 35091535, 2022). "Depletion of circ-E2F3 in xenograft models of RB decreased tumor growth." (PMID 36619866, 2022). "Furthermore, tumors from 32 kPa CM/Hep3B showed higher α-SMA and Collagen I compared to other groups, which revealed that stiffness facilitated the effects of HSCs on tumor growth-dependent E2F3 of HSCs (P < 0.05 by ANOVA)." (PMID 34873170, 2021). "We found that miR-141 was down-regulated in tumor tissues while E2F3 was up-regulated." (PMID 33981611, 2021). "It remained still a question whether the E2F3 transcription factor could play a role in the tumor formation and development of LUSC by binding to the ENO1 promoter, which required more sophisticated experiments for clarification." (PMID 34504528, 2021). "Besides, a suggestive relationship between E2F3 and survival indicated that a greater expression difference of E2F3 between normal and tumor tissue will possibly predict shorter survival of the patient affected by HNSCC." (PMID 33981611, 2021). "Consistently, E2F3-silencing significantly reduced the tumor volumes and weights." (PMID 32669100, 2020). "In addition, after knockdown RBAT1, the expression of E2F3 was largely reduced and the tumor proliferation was also suppressed." (PMID 32669100, 2020). "It has been suggested that miR-34a could have a role as tumor suppressor in NB tumorigenesis by directly binding to E2F3 mRNA and significantly reducingthe level of E2F3 protein." (PMID 32429447, 2020). "Moreover, we screened primary tumor tissue from stage 4S NB for E2F3 protein expression using immunofluorescence, and we found that high level of nuclear E2F3 expression was strongly associated with disease relapse or progression." (PMID 32429447, 2020). "In this study, we have proved that circ_0087378, as a newly discovered circRNA in ESCC, could sponge miR-140-3p to upregulate the expression of E2F3 and eventually serve as a tumor promotor in ESCC." (PMID 33680929, 2020). "To determine whether RBAT1 could activate E2F3 by recruiting HNRNPL to its promoter, we evaluated the status of E2F3 promoter transcriptional activity in tumor cell lines with different RBAT1 and HNRNPL expression levels using luciferase assays." (PMID 32669100, 2020). "E2F3 is crucial for controlling tumor cell proliferation rate and regulating cell cycle." (PMID 33604289, 2020).
tumor (continued). "The immunoblotting showed that ZNF300‐flag, used as bait, could bind to E2F3, indicating that ZNF300 might interact with E2F3 to function in the chemoresistance and aggressive behaviour of tumour cells." (PMID 33078469, 2020). "However, the E2F3 expression was positively related to tumor purity and neutrophil infiltration remarkably in GBM." (PMID 33381564, 2020). "As expected, the colony formation of tumor cell lines was decreased after E2F3 silencing." (PMID 32669100, 2020). "Additionally, through a more in-depth understanding of E2F3, it was revealed that there are intricate networks between E2F3 and miRNAs in regulating the occurrence, development and progression of tumours." (PMID 31423109, 2019). "Our results suggested that E2F3 might play a tumour-promoting role in the metastasis and progression of GC by regulating the miR-125a/DKK3 axis." (PMID 31423109, 2019). "E2f3, a member of the E2F family of transcription factors, is critical for the transcriptional activation of genes that control proliferation in both normal and tumor cells." (PMID 30275866, 2018). "Based on that, SOX4, E2F3 or 6q22.3 amplifications might represent potential targets in this tumor type." (PMID 30072631, 2018). "Our results indicated that GZZSZTW significantly increased the expression levels of multiple genes involved in promoting cell proliferation, most of which are highly expressed in tumor cells, such as Tnfaip2, Chi3l1, Tnf, Pfkfb3, Sox8, Jag1, Mafb, Pla2g7, Hnrnpa1, and E2f3." (PMID 30275866, 2018). "miR-377-3p exerted tumor suppressive function through down-regulation of E2F3." (PMID 28947999, 2017). "Moreover, a significantly decreased level of E2F1 and E2F3 was observed in tumor tissue of LLC mouse model with exposure to LF-MF." (PMID 28389657, 2017). "Clinically, we demonstrated that E2F3 was overexpressed in advanced tumor features." (PMID 28903320, 2017). "In the present study, we propose that E2F3 may have a tumor suppression effect in NSCLC, because the rs3806116 TT was a risk genotype that was associated with a poor NSCLC OS by decreasing E2F3 mRNA expression." (PMID 27557513, 2016). "Moreover, our results also demonstrated miR-377-3p exerted its tumor suppressive role on NSCLC through targeting E2F3." (PMID 27351135, 2016). "Knockout of E2F1 or E2F3 significantly delayed tumor onsets." (PMID 26512919, 2015). "PPIX inhibition of E2F3 was verified in other mesenchymal tumor cell lines." (PMID 25714015, 2015). "Overall, these data demonstrate that E2F3 knockdown impairs several important cellular processes, such as centrosome amplification and mitosis; and the reductions in percentages of cells undergoing mitosis correlates with impaired tumor growth." (PMID 26512919, 2015). "There was a significant delay in tumor latency associate with E2F1, E2F2 and E2F3 loss." (PMID 26682278, 2015). "We found that inactivation of either E2f1 or E2f3 can suppress tumor development in the retina." (PMID 25338120, 2014). "As both E2F3 isoforms were downregulated in miR-34a transfected cells, we performed isoform-specific rescue experiments to understand the specific contribution of E2F3a and E2F3b in miR-34a mediated tumor suppressor function." (PMID 22629428, 2012). "In addition to a significant up-regulation of PRC2/EED-EZH2 genes in LN metastasis, our microarray data showed an increase of E2F3 in 5 out of 6 lymph node metastasis compared to primary tumor." (PMID 23251464, 2012). "Furthermore, our results demonstrate that miR-34a can also regulate tumor angiogenesis by directly inhibiting angiogenic functions of endothelial cells by downregulating a number of key proteins including E2F3, SIRT1, survivin and CDK4." (PMID 22629428, 2012). "Finally, we took advantage of previously developed gene expression “read outs” resulting from experimentally controlled oncogenic pathway activation (src, b-catenin and E2F3) to assess activation status in individual tumor samples." (PMID 21479231, 2011).
tumor (continued). "We examined whether there was a correlation between KIF14 and E2F3 mRNA expression levels in the 55 untreated tumors and various tumor phenotypes." (PMID 19190782, 2009). "Immunohistochemistry confirmed KIF14 and E2F3 protein overexpression in tumor cells." (PMID 19190782, 2009). "This in addition to the nuclear localization of E2F3 may represent the functional intactness of both proteins in tumor cells." (PMID 19190782, 2009). "Immunohistochemistry was done to confirm KIF14 and E2F3 protein expression in tumor cells." (PMID 19190782, 2009). "Genomic amplification of the E2F3 locus may consequently contribute to tumor development both by accelerating the cell cycle and by raising the threshold for apoptosis via inactivation of p14ARF." (PMID 18237450, 2008). "By combining the prediction results from SCENIC and the JASPAR database, the expression differences between tumor and normal tissues, and correlating these with prognosis, we finally deduced E2F3 may be the key transcription factor and verified this by luciferase reporter gene assays." (PMID 40299364, 2025). "Moreover, the E2F3 expression levels were decreased in tumor xenografts of the sh-POU6F2-AS2 group." (PMID 37053020, 2023). "Additionally, exosomal miR-194-5p derived from irradiated dying tumor cells induces the arrest of the G1/S cell cycle and enhances the survival of tumor-repopulating cells by regulating the expression of E2F transcription factor 3 (E2F3)." (PMID 36139006, 2022). "The GSEA revealed that the genes correlated with PLCB1, including HEY1, EZH2, VEGFA, E2F3, and STC1, were enriched in angiogenesis, suggesting that the increased expression of PLCB1 might be associated with HCC recurrence via tumor-associated angiogenesis." (PMID 35707353, 2022). "Therefore, stiffness-E2F3 promoted HSCs to generate and release tumor-promoting factors, FGF2." (PMID 34873170, 2021). "In addition, by targeting E2F3, miR-564 acts a tumor suppressor in GC." (PMID 34532281, 2021). "In addition, epigenetic factors, such as miR-195 and miR-148a, could also target E2F3 mRNA, downregulate its expression and result in tumor growth inhibition." (PMID 32669100, 2020). "Elevated E2Fs (not E2F3) were associated with adverse tumor features and poorer outcome." (PMID 32064771, 2020). "Additionally, the expression of SNHG5, miR-205 and E2F3 in the tumours was detected." (PMID 31292168, 2019). "However, cytoplasmic and nuclear E2F3 expressions were correlated strongly with the tumor sizes (p=0.021 and p<0.001), clinical stages (p=0.030 and p=0.003), MVI (p=0.002 and p<0.001), and metastatic state (p=0.001 and p=0.016), except for histological grade (Fuhrman grade) (p=0.385 and p=0.028)." (PMID 28903320, 2017). "Thus, it was concluded that down-regulation of E2F3 may be a molecular mechanism by which miR-432 exerted its functions as a tumor suppressor in human LAD cells." (PMID 26942465, 2016). "The fact that germline variant frequencies were not retained in matched FFPE samples may be related to somatic changes in tumor DNA and not to technical errors, as exemplified in the E2F3 and VEGFA germline variants that were validated with Sanger sequencing." (PMID 26039550, 2015). "Our bioinformatic analysis identified more than 20 potential miR-1206 targets, including E2F3 (a transcription factor that regulates cell proliferation) and TP53INP1 (a tumor suppressor gene regulating autophagy)." (PMID 38612604, 2024). "E2F1, E2F3, and E2F4 are all transcription factor E2F family members, which are critical in controlling tumor-suppressor protein production and the cell cycle and are also targeted by small-DNA tumor virus transformation proteins." (PMID 37504265, 2023).